CD4 (CD4 molecule)
Diseases named in the same sentence as CD4 in open-access papers (continued):
Sharing a sentence is not in itself a finding about the gene and the disease.
tumor (continued). "Although CD4+ and CD8+ T cells settled in the tumor show a higher degree of activation than the circulating counterpart, they occur with a more exhausted phenotype." (PMID 32182707, 2020). "CD4 and CD8 T cells homeostasis is a critical factor, in both primary tumor and at metastatic sites orchestrating anti-tumor activity." (PMID 33245727, 2020). "The DVL3 tumours have a lower proportion of both cytotoxic CD8 + T-cells (0.187% vs. 2.05%, p = 0.01) and CD4 + T-cells (0.36% vs. 4.31%, p = 0.01) compared to the TRAMP C1 tumours." (PMID 33003551, 2020). "Both studies confirm that DNA electrotransfer increased INF-γ and IL-12 secretion inducing infiltration of CD4+/CD8+T-cells and NK cells into the tumor site." (PMID 32784598, 2020). "In the IRE/STING combination group, the number of activated DCs in the tumor increased, and the number of CD8+ and CD4+ cells also increased." (PMID 33114476, 2020). "The tumor microenvironment of the HCC is infiltrated with different types of immune cells, mainly T-cells (CD8+, CD4+, Treg), natural killer cells and myeloid cells (myeloid-derived suppressor cells and tumor-associated macrophages)." (PMID 33086471, 2020). "The significant increase in Tregs and exhausted CD4 and CD8 T cells in tumor tissues indicated an immune suppressive environment." (PMID 33293583, 2020). "In this context, the combined assessment of CD3, CD4 and CD8 IHC and tumour hypoxia by the Winters Metagene signature was found to be an independent predictor for survival when adjusted for clinical covariates, KRAS status and CRIS-B subtype." (PMID 32684627, 2020). "Most of the cell cultures comprised HPV16-specific CD4+ T cells and infrequently CD8+ T cells with the capacity to kill target tumor cells." (PMID 33425717, 2020). "On the other hand, Doxil® treatment, if anything, tended to increase levels (n.s.)of both tumor infiltrating CD8+ and CD4+ T cells." (PMID 33086690, 2020). "Both ICB therapies achieved a reduction in tumor volumes by recruiting tumor-infiltrating CD8+ and CD4+ T cells." (PMID 32774773, 2020). "This phenotype corresponded to increased CD4+ and CD8+ T cell tumor-infiltration and resultant increases in anti-tumor T lymphocyte IFN-γ production." (PMID 33324425, 2020). "The percentage of tumor cells overexpressing CD155 had a significant correlation with cell counts of CD4+, CD4+/PD-1+, CD8+, and CD8+/PD-1+ TILs." (PMID 32411795, 2020). "C4 was enriched with immune cells including activated B cells, CD4+ T cells, CD8+ T cells, neutrophil cells, macrophages and dendritic cells by the tumor immune estimation resource (TIMER)." (PMID 32719796, 2020). "Compared to that in the PBMCs, the ratios of immune checkpoint-positive exhausted CD4+ T cells and CD8+ T cells were distinctly higher at the AG tumor sites." (PMID 33614475, 2020). "Although the impacts of LAG-3-MHC-II interaction on CD4+ T cell immunity have been well studied, it was poorly understood as to how LAG-3 negatively regulates CD8+ T cell-mediated anti-tumor immunity." (PMID 32787882, 2020). "CD4+Foxp3+Helios+ Treg cells co-expressed the suppressive molecules PD-1, CTLA-4, and CD39, suggesting that the phenotype of these Treg cells in the tumor of CRC patients is highly suppressive." (PMID 32674255, 2020). "In a tumor, CD11b+CX3C1+ macrophage subset has been shown to induce CD4+ Foxp3+ cells, and its depletion leads to reduced tumor growth." (PMID 33371444, 2020). "The results showed that in MDA-MB-231 tumor-bearing mice, AXL-CAR-T cells that coexpressed C7R presented higher proliferation levels than AXL-CAR-T cells, and the CD8 : CD4 ratio was significantly higher." (PMID 31998790, 2020). "Anti-tumor lymphocyte cell subpopulations, like activated CD4+/CD8+ T cells, effector memory CD4+/CD8+ T cells, and natural killer T cells were enriched in the low-risk signature group (P < 0.05)." (PMID 33013820, 2020).
tumor (continued). "Using multiplex immunohistochemistry, T-cell (CD4, CD8) and myeloid cell (CD11b) expression were investigated in excised tumours." (PMID 33003551, 2020). "Tumoural parenchyma was immunohistochemically counted manually for the number of CD8, CD4 and Foxp3 cells." (PMID 32758195, 2020). "Our findings show that BMP7 regulates proinflammatory responses in the tumor microenvironment by suppressing mitogen-activated protein kinase 14 (MAPK14) signaling in macrophages and CD4+ T cells." (PMID 32973129, 2020). "The cell debris resulting from NK-mediated tumor destruction fuels DCs with antigens and enhances their presentation to CD4+ and CD8+ T cells, indirectly improving anti-tumor immunity." (PMID 32075343, 2020). "Several studies previously showed the crucial importance of activating the CD4+ T cell compartment, in addition to cytotoxic CD8+ T cells, a requirement for the induction of spontaneous and immunotherapy-induced anti-tumour responses." (PMID 32498431, 2020). "Tumors from these transgenic mice had increased numbers of infiltrating CD4+ Th2 cells compared to WT mice, suggesting that in this model TSLP and Th2 cells exerted tumor-suppressive function in the context of a systemic Th2-polarized environment." (PMID 33042121, 2020). "There are various subtypes of CD4+ T cells and CD8+ T cells, and the difference in one cell-surface marker can be a switch for a completely opposite function in tumor progression." (PMID 33121123, 2020). "Previous studies have shown that effective tumour killing and eradication by CD8+ CAR T cells are reliant on the presence of CD4+ CAR T cells." (PMID 31803974, 2020). "On the contrary, CD4+ TH2, producing IL-4, IL-5, and IL-13, generally promote tumor growth and development." (PMID 32235370, 2020). "Granzyme B and Fas were elevated in both G-CSFR−/− CD4+ and CD8+ treated tumors, suggesting that G-CSF plays a role in both T helper and cytotoxic T cell activity in the tumor microenvironment." (PMID 33042110, 2020). "The immune-inflamed phenotype is characterised by the presence of CD4+ and CD8+ T cells in the tumor parenchyma." (PMID 33178839, 2020). "Linear regression analysis in cohorts B and C demonstrated a positive linear relationship between the percentage of dHGP scored at the tumour–liver interface and CD8+ T cells, as well as the CD8/CD4 ratio." (PMID 32418992, 2020). "In vitro, in vivo, and clinical blockade of macrophage CSF-1R with a monoclonal antibody (RG7155) strongly reduced TAM migration and infiltration into the tumor site and the CD8+/CD4+ T cell ratio." (PMID 32509781, 2020). "The immunologic effect of AE37 vaccination has also been shown to increase IFN-γ + CD4 + responder cells which in turn assists in strong in vivo and in vitro autologous CTL lysing of tumor cells." (PMID 32323103, 2020). "The results revealed that the CD4+/CD8+ cell ratio was significantly different in both the peripheral blood and tumor tissue when the low level was compared with the high level of the lymphocyte subsets." (PMID 32131750, 2020). "In tumor biopsies of patients, reduced CD163+ M2-TAMs was inversely correlated with the increased CD8+/CD4+ T cells ratio." (PMID 32103760, 2020). "Individual depletion of CD4 T cells, CD8 T cells and CXCL9, CXCL10, abrogated the anti-tumor activity of combined therapy." (PMID 33167311, 2020). "Other experiments have also shown that increases in the numbers of CD4+ T and CD8+ T cells in the TME are closely related to tumor prognosis." (PMID 32823603, 2020). "We found that the recruitment in the tumor of cytotoxic cells, namely the terminally differentiated CD4+ and CD8+ T cells (TEFF), is impaired, whereas the effector memory CD4+ T cells (TEM) are more attracted in this site." (PMID 32182707, 2020). "After tumor digestion with collagenase, single-cell suspensions were stained with fluorescence-labeled CD45, CD8, and CD4 antibodies." (PMID 32226302, 2020).
tumor (continued). "CD163 positive cells were significantly positively correlated with CD4 (p = 0.0405) and CD8 (p = 0.0032) positive cells in the tumor." (PMID 33244312, 2020). "Gal3 impairs IFN-Ƴ secretion by CD4+ and CD8+ T lymphocytes; indeed, GCS-100 combined with therapeutic vaccination promotes cytotoxicity and cytokine secretion, resulting in increased tumor rejection." (PMID 32168866, 2020). "For some cancer mouse models, neutrophil depletion led to a decrease in CD4 and CD8 T cell activation, thereby enhancing tumor growth, while in others their presence was able to suppress CD8 T cells and promote metastasis." (PMID 32983165, 2020). "In NSCLC tumor samples, different subsets of CD8+ T cells, conventional CD4+ T cells, and Treg cells have been found." (PMID 32265933, 2020). "CD3, CD4 and CD8 expressing T lymphocytes were found only in the blood vessels near the tumour lobules and retinal regions and very sparsely present in other regions." (PMID 32576886, 2020). "CD4+ T cells with cytotoxic capabilities occur in DLBCL and their presence correlates with the MHC class II expression by tumor cells." (PMID 31261914, 2019). "IL16 is a cytokine that recruits CD4+ immune cells, and its downregulation in FVPTC can suggest immunosuppression in the tumor microenvironment." (PMID 31443155, 2019). "The immune infiltrate in pre-treatment tumor samples of both patients was composed of immature T cells expressing TdT, CD1a and CD5, CD4 and CD8." (PMID 31639039, 2019). "The effective immune cells mainly include CD4+ T cells, CD8+ T cells, NK cells, and tumour-inhibiting M1-TAMs, which are in a state of exhaustion or suppression in the microenvironment." (PMID 30777100, 2019). "Systemic administration (intraperitoneal, i.p.)of the mCD39-specific ASO in MC38 tumor bearing mice resulted in a specific and dose-dependent downregulation of CD39 protein in tumor infiltrating CD4+ Tregs as well as TAMs." (PMID 30871609, 2019). "Tregs, especially CD4+CD25+Foxp3+, are one of the most studied immune cells owing to their specific inhibitory influence on HCC tumour growth and progression." (PMID 30893948, 2019). "At the tumor site, treatment decreased MDSCs and Treg, and increased the number of CD69+CTL and effector CD4+ cells." (PMID 31214178, 2019). "For example, local IL-33 production in a mouse model of hepatocellular carcinoma was shown to enhance CD4+ and CD8+ anti-tumor activity, warranting a re-evaluation of the use of IL-33-neutralizing drugs in tumor models." (PMID 30949175, 2019). "We designed our flow cytometry panel to characterize putative TAI subsets within the tumor infiltrated CD8+ and CD4+ T cells." (PMID 31412943, 2019). "CD4+ CTL and Th1 subsets mainly exert anti-tumour activity, while the regulatory T cells (Tregs) have potent tumour-promoting activity." (PMID 31519961, 2019). "Using a mouse AB1 malignant mesothelioma model, it was revealed that treatment of tumor-bearing mice with DCs loaded with either tumor cell-derived EVs or tumor lysate results in infiltration of CD4+ T cells, CD8+ T cells, and DCs into tumor tissues." (PMID 31680949, 2019). "In another study, the same treatment combination showed a higher elevation of CD4+ and CD8+ T cells and IL-12, IFN-y and TNFα together with a delay in tumour growth and improved survival in mice treated with the combination therapy." (PMID 31111237, 2019). "Compared to adjacent tumor-free colon, CD4+ FOXP3+ T cells and ST2-positive Tregs were more abundant in human CRC lesions, yet ST2 expression levels were unchanged in tumor tissue." (PMID 31165767, 2019). "Differently, systemic administration of the P2X7 blocker A740003 in wild-type mice left unaltered the number of tumor-infiltrating CD8+ and Treg lymphocytes but increased CD4+ effector cells and decreased their expression of CD39 and CD73." (PMID 30655604, 2019).
tumor (continued). "Fractions of CD4+ and CD8+ tumor infiltrating T cells were significantly increased after PD-1 antibody treatment only in recipients of shLDH-A deficient B16-F10 tumors." (PMID 30934955, 2019). "The number of infiltrated CD4+ helper T cells, FoxP3+ regulatory T cells, and CD45R+ B lymphocytes was also small in the tumor lesions of PKF and PKF2h mice." (PMID 30659170, 2019). "Tissue sections from intracranial CT2A-dmEGFRvIII-Luc (A) and SMA560-dmEGFRvIII-Luc (B) tumors were analyzed for the expression of PD-1 and FoxP3 on CD4+ and CD8+ T cells and PD-L1 on tumor cells." (PMID 31142380, 2019). "This was demonstrated using isolated CD4 T cells from ovalbumin- (OVA-) immunized mice with pericytes incubated in the presence of OVA, where ICAM-1 expression on tumor-derived pericytes engaged LFA-1 on CD4 T cells to induce anergy." (PMID 31205449, 2019). "(A) Absolute number and (B) Fold change in number of circulating lung CD4 and CD8 T cells of tumor bearing CCSP-rtTA; TetO-EGFRL858R mice in the absence (−) and presence (+) of erlotinib for 2 weeks." (PMID 31291990, 2019). "Although the overall percent of tumor-infiltrating T cells remained similar, tritherapy increased the ratio of effector CD4+ T cells-to-regulatory T cells, CD4+ T-cell cytokine production and proliferation, and CD8+ T-cell cytolytic activity in the tumor." (PMID 31747946, 2019). "Absolute number of (C) CD4 and (D) CD8 T cells normalized to weight of lungs of tumor bearing CCSP-rtTA; TetO-EGFRL858R or CCSP-rtTA; TetO-EGFRL858R + T790M mice in the absence (−) and presence (+) of erlotinib for 2 weeks or taken off doxycycline diet." (PMID 31291990, 2019). "In only one tumour high expression levels of CD2, CD3, CD4, CD8 CTLA-4 and PD-1 were found, suggesting an inflammatory phenotype (not shown)." (PMID 31747973, 2019). "Differentiating between CD4+ and CD8+ T-cell markers did result in different rankings, consistent with evidence that these T-cell types play divergent roles in the tumor microenvironment." (PMID 31360302, 2019). "TAAs are subsequently processed by antigen-presenting cells (APC) and presented to CD4+ T cells, or cross-presented to CD8+ T cells, to promote an adaptive immune response, including immunological memory, against the tumor." (PMID 31262361, 2019). "Class II HER2-DC1, when combined with anti-PD-1 antibody, quadrupled the survival rate with increased anti-HER2 CD4+ Th1 immune response and increased CD4+ and CD8+ T cells infiltration within the tumor." (PMID 31475002, 2019). "TRAPs-elicited CD4+ T cells (TTRAP) directly inhibit the anti-tumor IFN-γ response of CD4+ T and CD8+ T cells and also induce IL-10+ Bregs, which creates a favorable environment to facilitate tumor growth and metastasis." (PMID 31300052, 2019). "In further support, depletion of intratumoral CD4+ and CD8+ T-cell in mouse tumor models generated a more dysfunctional tumor vasculature with an increase in hypoxic areas." (PMID 31572387, 2019). "The proportions of monocytes, alveolar macrophages, CD4+ conventional T cells (Tconvs), CD8+ T cells, and B cells in the lungs decreased by 2–3 weeks after tumor implant, but the absolute numbers of these cells did not change." (PMID 31488209, 2019). "CD4+ T cells have been shown to eradicate tumors independent on CD8+ T cells and were more efficient in tumor rejection than CD8+ T cells." (PMID 31780946, 2019). "Early (day 23) time-point analysis of CPR treated tumors showed a largely myeloid-dominated tumor, with small and approximately equal fractions of CD8+, CD4+, and Tregs." (PMID 31409394, 2019). "This confirms that a more active state of effector CD8+ T cells, combined to a lower infiltration of CD4+ T regulatory cells or a low expression of the PDL1, provides a more effective tumor micro-environment with an improved survival." (PMID 31756926, 2019).
tumor (continued). "The anti-tumor effects of HMGN1, anti-CD4 depleting antibody, and their combined treatment were monitored in the Colon26 or the B16F10 subcutaneous murine models." (PMID 30696484, 2019). "Combined use of ANF and anti-PD-L1 antibody significantly increased infiltration of CD8+, CD4+, and CD3+ T lymphocytes into tumor tissues, and upregulated the expression of IFNγ and TNFα." (PMID 30850589, 2019). "Taken together, our results indicated that both CD4+ and CD8+ T cells potently inhibit in vivo tumor growth when they are engineered by high-affinity 19305DP-TCR." (PMID 30626427, 2019). "PD-1-mediated suppression of tumor-targeted immune mechanisms involves the interaction of this ICI expressed on activated, anti-tumor CD4+ and CD8+ effector T cells with PD-L1 expressed on tumor cells." (PMID 31616428, 2019). "Tumor-infiltrating lymphocytes (TILs) are largely CD8+ T cells, CD4+ T helper (Th) cells and Treg cells." (PMID 31430935, 2019). "Maitake α-D-glucan (YM-2A; Grifola frondosa) has been found to enhance host anti-tumour action, activating CD4+ and CD8+ lymphocytes in the spleen and CD8+ cells in tumour-draining lymph nodes." (PMID 31684030, 2019). "Cryo-thermal-activated eosinophils play a crucial role in M1 macrophage polarization, DCs maturation, functional differentiation of CD4+ T cells, generation of cytotoxic CD8+ T cells, and finally triggering long-lasting anti-tumour memory immunity." (PMID 31519961, 2019). "Tumor growth evoked an increase of CD4 and CD8 Tef/Tem cells in the spleen, CD4 Tef/Tem in LN, but a decrease of the portion of CD4 and CD8 Tcm cells in spleen and LN." (PMID 31717542, 2019). "This was confirmed in the current set of 43 tumours, by determining the numbers of lymphocytes (CD3+, CD4+, CD8+, FoxP3+; using immunofluorescence (IF)) and macrophages (CD68+, CD163+, CD68+CD163+; using IF)." (PMID 31337000, 2019). "Our data demonstrate that increasing adiposity decreased the percentage of total CD3+ T cells, CD4+ helper T cells, and CD8+ cytotoxic T cells in the spleen, tumor draining lymph node, and TME." (PMID 31835454, 2019). "The results showed that most commonly detected immune cells at the tumor site were CD8+ TILs, followed by CD4+ TILs; Foxp3+ regulatory T (Treg) cell were 12%." (PMID 31620360, 2019). "Therefore, we tested whether NUP214-specific CD4+ T-cells are activated by autologous tumor cells." (PMID 31221207, 2019). "Altogether, Th1 CD4+ T cells, CD8+ cytotoxic T cells, NK and DC cells, along with their characteristic production of IFN-γ, are important anti-tumour effectors of our vascular-PDT protocol with redaporfin." (PMID 31906092, 2019). "The effector tumor Ag-specific and cancer-reactive CD8+ and CD4+ T cell response from the endogenous repertoire is enhanced both in the tumor and tdLN and precedes delays in tumor growth." (PMID 30961656, 2019). "The combination of p-Tvax and the OX86 mAb modified the tumor microenvironment in a manner that led to more optimal anti-cancer immune conditions as supported by higher abundance of both CD8+ and CD4+ T cells, and reduced percentages of Tregs." (PMID 31428586, 2019). "VLP induce robust CD4+ and CD8+ T-cell responses and have been shown effective in delivering tumour antigen peptides for immunotherapy." (PMID 30729137, 2019). "Intracranial CT2A-dmEGFRvIII-Luc (A-D) and SMA560-dmEGFRvIII-Luc (E-H) tumors were analyzed for the expression of PD-1 on CD4+ and CD8+ T cells, FoxP3 on CD4+CD25+ T cells and PD-L1 on tumor cells." (PMID 31142380, 2019). "As expected, FTY720 treatment reduced the number of CD4+ and CD8+ T cells in the tumour (Fig EV3A and B)." (PMID 31283095, 2019). "Once generated in the draining lymph nodes, LLC-specific effector CD4 (Th1) and CD8 (CTLs) would migrate into tumor tissue to produce IFNγ and kill tumor cells." (PMID 30972427, 2019).